DAPK3 (death associated protein kinase 3)
Diseases named in the same sentence as DAPK3 in open-access papers (continued):
Sharing a sentence is not in itself a finding about the gene and the disease.
tumor (continued). "This approach would inactivate the DAXX pathway for tumor promotion, and consequently restore the activity of the DAPK1 and DAPK3 tumor suppressors." (PMID 26097870, 2015). "Overexpression of DAPK3 induced changes in tumor cell morphology, suppressed cell aggregation, and promoted cell apoptosis." (PMID 25887170, 2015). "The expression level of DAPK3 have been shown to regulate the survival and apoptosis in tumor cells." (PMID 25887170, 2015). "A recent study reported that DAPK3 might drive tumor‐intrinsic immunity through the cGAS‐STING‐INF‐β pathway, which has been increasingly highlighted as a central interface between the cellular DDR system and tumor immunity." (PMID 39254643, 2024). "DAPK3 was reported to be a target of miR-17/20a and played an important role in preventing miR-17/20a depletion-induced genome instability or miR-17/20a overexpression triggered tumor formation." (PMID 34422899, 2021). "Thus, one of the tumor‐promoting activities of AKT is repression of the tumor‐suppressing kinase DAPK3." (PMID 30548122, 2019). "In view of this evidence, DAPK3 has been regarded as a tumor suppressor." (PMID 30287790, 2018). "Similarly, in this study, DAPK3 was shown to be another tumor suppressor that may be inhibited by AKT." (PMID 27126362, 2016). "In NSCLC, VIRMA mediated the m6A modification of DAPK3, facilitating YTHDF2/3-mediated DAPK3 post-transcriptional degradation and promoting tumor growth." (PMID 40723784, 2025). "DAPK3, like other members of the DAPK family, is a pro‐apoptotic kinase with a reported tumour‐suppressor activity." (PMID 32306542, 2020). "In many types of cancer, including PCa, tumor suppressors, such as DAPK1 and DAPK3, are downregulated, a process that facilitates cancer metastasis." (PMID 26097870, 2015). "DAPK3, also known as ZIPK, is a tumor suppressor that activates antitumor immunity via STING." (PMID 36802409, 2023). "In addition to DAXX, immunohistochemistry studies will include DAPK1 and DAPK3 so as to establish a relationship between DAXX and the DAPK1/3 tumor suppressors." (PMID 26097870, 2015). "In contrast to DAPK1 and DAPK3, DAPK2 has not been identified as a tumor suppressor in solid tumors." (PMID 30287790, 2018).
cancer (31 papers, 2008 to 2025). A tumor composed of atypical neoplastic, often pleomorphic cells that invade other tissues. "While missense mutations in the kinase domain of DAPK3 had been observed in various carcinomas, there was only circumstantial evidence linking it to the heart." (PMID 35373735, 2022). "Using the bioinformatic prediction algorithm CanPredict, death‐associated protein kinase 3 (DAPK3) was identified as a cancer‐associated kinase, where every mutation was predicted to be a pathogenic mutation." (PMID 30548122, 2019). "Mutation and deletion of DAPK3 is a major setback that can lead to a survival advantage in cancer cells." (PMID 27126362, 2016). "Overall, the mutations and altered expression of DAPK3 are associated with the proliferation of cancer cells and the development of chemoresistance." (PMID 25887170, 2015). "Zipper interacting protein kinase (ZIPK), also known as death associated protein kinase 3, is a serine/threonine kinase that mediates apoptosis in cancer cells." (PMID 25797270, 2015). "These DAPK3 mutations identified in cancer patients can significantly suppress the activity of the kinase." (PMID 24817905, 2014). "It has been reported that DAPK3 is frequently methylated or mutated in many cancer types." (PMID 27126362, 2016). "DAPK3 is a relatively novel cancer-associated kinase with functional mutations." (PMID 24817905, 2014). "Key lncRNAs, such as lnc-RMDN2-AS1, co-expressed with DAPK3, suggest a role in apoptosis regulation—a critical pathway that is often disrupted in cancer." (PMID 40248203, 2025). "Previous studies showed that DAPK family members, including DAPK1, DAPK2 and DAPK3 play a crucial regulatory role in malignant tumor development, in terms of cell apoptosis, proliferation, invasion and metastasis." (PMID 34422899, 2021). "Conversely, in cells and tissues, DAPK1 and DAPK3 are downregulated in cancer contexts [18; Submitted]." (PMID 26097870, 2015). "An in-depth study of the relationship between miR-637 and DAPK3 may broaden the understanding of the molecular mechanism of DAPK3 in cancer." (PMID 36175921, 2022). "However, there is still no research on the relationship between the expression and function of miR-637 and DAPK3 in cancer." (PMID 36175921, 2022). "Moreover, DAPK3 inhibition appeared to have a broader effect in repressing pathways involved in cancer proliferation than ibrutinib." (PMID 32306542, 2020). "More precisely, pAKT expression was low in BPH, whereas DAPK3 was strongly expressed in cytoplasm; however, in carcinoma, we noticed a higher expression for pAKT in the nucleus in higher Gleason score and decreased expression of DAPK3 in higher Gleason score samples." (PMID 27126362, 2016). "DAPK3 has been show to function in apoptosis, autophagy, actin filament regulation, cell migration, smooth muscle contraction, mitosis, and development of several types of cancer." (PMID 25887170, 2015). "Finally, we silenced DAPK3 by siRNA and determined whether inhibition of DAPK3 reverses pAKT expression in cancer cells." (PMID 27126362, 2016). "Therefore, the expression level of DAPK3 could be a marker for cancer migration, invasion, and survival." (PMID 25887170, 2015). "Our data suggest that DAPK3 inhibition could be an alternative to ibrutinib treatment in CLL, particularly in cases where resistance is associated with BTK/ PLCγ2 mutations, but also more generally in cancers characterised by DAPK1‐silencing, which is a common marker of poor prognosis." (PMID 32306542, 2020). "However, DAPK3 mutations have not been detected in all cancer samples." (PMID 25887170, 2015). "On the other hand, a recent study demonstrated that DAPK3 promotes cancer cell proliferation rather than the promotion of apoptosis in many types of cancer cells." (PMID 30287790, 2018).
cancer (continued). "Additionally, it was reported that miR-19b-1 may also target caspase 8 (CASP8), death-associated protein kinase 3 (DAPK3), and programmed cell death 1 ligand 2 (PDCD1LG2), all genes known to be involved in apoptosis, further suggesting the anti-apoptotic function of the miR-17-92 cluster in cancer." (PMID 19440450, 2008).
DAPK3 also shares sentences with these, for which no sentence is quoted: cervical cancer (3 papers); colon carcinoma (2); ovarian cancer (2); Stroke (2); Alzheimer disease (1); atherosclerosis (1); brain injury (1); breast tumor (1); cardiac disease (1); chronic lymphocytic leukaemia (1); complication (1); congenital heart disease (1); diabetic (1); dilated cardiomyopathy (1); genetic disorder (1); heart failure (1); hepatoblastoma (1); Hyperglycemia (1); hypertensive cardiovascular diseases (1); infection (1); Insulin resistance (1); ischemia (1); ischemic stroke (1); lung squamous cell carcinoma (1); lymph node metastases (1); medulloblastoma (1); metabolic disorders (1); metastatic tumors (1); myocardial hypertrophy (1); neural tumours (1).
A further 9 diseases each share a sentence with DAPK3 in 1 paper.